IL4R (interleukin 4 receptor)
Diseases named in the same sentence as IL4R in open-access papers (continued):
Sharing a sentence is not in itself a finding about the gene and the disease.
eosinophilia (continued). "Finally, to ascertain that the deletion of IL4Rα in the eosinophils did not affect their abilities to respond to the chemoattractants, we experimentally induced IL-5/eotaxin-mediated lung eosinophilia in the WT and mye-IL4Rα−/− adult mice." (PMID 34326406, 2021). "Therefore, our infection model indicated CCR3-dependent processes and recruitment of residual eosinophilia were sufficient to exert immune control of fecund infections in the absence of IL-4R signaling." (PMID 32571840, 2020). "In the current study, we reinforce the primary role of eosinophilia in driving immune control of adult filarial nematode infection, yet demonstrate that eosinophil-mediated immune resistance can proceed in the absence of IL-4R signaling." (PMID 32571840, 2020). "The increased adult worm burden at a late time point of infection in animals lacking eosinophilia (IL-5−/−, IL-4R−/−/IL-5−/−, dblGATA) further suggests that the extended microfilaremia is rather due to this prolonged adult worm survival than an impaired MF clearance." (PMID 31109364, 2019). "WT mice, but not IL-4Rα−/− mice, develop a pronounced eosinophilia." (PMID 24475277, 2014). "The addition of IL-4Rα-/- BMM did not alter the level of TH2-driven eosinophilia." (PMID 22292924, 2012).
colon carcinoma (15 papers, 2002 to 2023). "IL4R has been widely studied in association with colon tumors, which gave us vital help in understanding why severe UC might develop into colon tumors." (PMID 39872548, 2023). "AP-1 (human atherosclerotic plaque-specific peptide-1)-conjugated liposomal conjugate specifically targeted at IL4Rα, showed an anti-cancer effect on IL4Rα-overexpressing colon cancer cells." (PMID 33419470, 2021). "Blocking of IL4R with IL4Rα antagonist or anti-IL4 neutralizing antibodies sensitized CD133-expressing colon cancer stem cells to conventional the chemotherapeutics oxaliplatin and 5-FU." (PMID 33419470, 2021). "IL-4/IL-4R in colon cancer cell lines Liu and colleagues found IL-4 and IL-13 increased nicotinamide adenine dinucleotide phosphate oxidase 1-related proliferation in HT-29 and DLD-1 human CC cells." (PMID 33450900, 2021). "Previous studies have suggested that IL4Rα is involved in promoting tumor development in colon cancer." (PMID 34681866, 2021). "Nevertheless, the density of M1 macrophages infiltrated into the tumor in colon cancer is much lower than that of TAMs, whose profile is favored by IL4Rα expression, as well as by IL-4 from tumor cells in the tumor microenvironment." (PMID 34681866, 2021). "Recent reports showed that IL4Rα and IL13Rα1 are overexpressed and activated in various types of epithelial tumor such as malignant glioma, ovarian, lung, pancreas, and colon carcinoma." (PMID 31540495, 2019). "Taken together, these data provide evidence demonstrating that IL-4 and IL-13 upregulate NOX1 in colon cancer cells though the IL-4R/STAT6 pathway, and that GATA3 plays an important role in the transcriptional regulation of NOX1." (PMID 28498822, 2017). "We confirmed by real time RT-PCR that IL-4Rα mRNA is present in all of the human colon cancer cells utilized." (PMID 28498822, 2017). "Epithelial interleukin-4 receptor expression promotes colon tumor growth and mediates drug resistance in colon cancer stem cells." (PMID 26556872, 2015). "The effects of IL-4 signaling have been studied extensively in the development of colon cancer: one study found pro-proliferative effects of IL-4Rα signaling in mouse colon tumors, as well as human and mouse colon adenocarcinoma cell lines examined in vitro." (PMID 24672527, 2014). "To examine the relationship between exogenous IL-4 or IL-13 exposure and the expression of NOX1, we first determined whether the NOX1-expressing colon cancer cell lines under study possessed IL-4Rα, as has been reported previously." (PMID 28498822, 2017). "In this study we confirmed that the complete absence of IL4Rα during CAC was directly related to a significant reduction in the number of colonic tumors." (PMID 34681866, 2021). "The relationship between IL-4Rα and NOX1 in these tumors and adjacent normal tissues suggests that the conditions exist in the clinic to support a mechanistic relationship between IL-4 and colon cancer proliferation." (PMID 28498822, 2017). "However, we also found that the expression or non- expression of IL4Rα in macrophages and a TAM phenotype in CAC were not the main factors responsible for the initial changes leading to the promotion of colon tumor development." (PMID 34681866, 2021).
colorectal cancer (13 papers, 1992 to 2025). A primary or metastatic malignant neoplasm that affects the colon or rectum. "Nevertheless, a tendency towards an inverse association was observed between IL4R-regulated eosinophils and colorectal cancer risk." (PMID 39181688, 2024). "The IVW method was employed to examine the association between eosinophils regulated by gene IL-4, IL-5, IL-13, IL-4R, and IL-5RA and the risk of colorectal cancer and skin malignancies." (PMID 39181688, 2024). "In addition, reduction of IL4R signaling was associated with increased initiation of colorectal cancer development, but reduced cancer progression." (PMID 33419470, 2021). "Activation of the Extracellular signal-regulated kinase (ERK) pathway via IL4/IL4R signaling plays a critical role in the proliferative phase of preosteoclasts, contributing to colorectal cancer bone metastasis." (PMID 40656893, 2025). "Colorectal cancer-related cancer-initiating cells evade immune surveillance through IL4/IL4R-mediated inhibition of T cell proliferation." (PMID 33419470, 2021). "We found that both cytokines increased the expression of NOX1 (but not other NOX species) over a period of 12 to 48 h in a panel of human colorectal cancer cell lines that possess the Type II IL-4R." (PMID 28498822, 2017). "To investigate the clinical relevance of our findings, we examined the relationship between expression levels of NOX1 and IL-4Rα in human colorectal cancer surgical specimens and adjacent uninvolved bowel mucosa by real time RT-PCR." (PMID 28498822, 2017). "Interleukin-4 receptor (IL-4R) and Epidermal Growth Factor receptor (EGFR) were assessed as factors associated with adenoma-carcinoma progression in colorectal cancer and tumour invasion." (PMID 1419612, 1992). "Interestingly, this arginine variant of IL4R (Q576R allele) was also associated with significantly increased risk of colorectal cancer in a British study, but there was no apparent association with mortality." (PMID 37860183, 2023). "In previous pre-clinical studies, we examined the contribution of interleukin 4 receptor (IL4R) signaling in the progression and metastasis of colorectal cancer (CRC)." (PMID 37860183, 2023). "Circ-3823, circ-IL4R, and circ-N4BP2L2 were significantly overexpressed in colorectal cancer cells, which indicates a poor prognosis in colorectal cancer patients." (PMID 36291546, 2022). "Whether a large number of differentially expressed circRNAs, such as circ-3823, circ-IL4R, and circ-CUL2 in colorectal cancer, could become effective targets for curcumin in the treatment of colorectal cancer remains to be further clarified." (PMID 36291546, 2022). "Colorectal cancer (CRC) cases (1502) and controls were genotyped for six coding IL-4Rα SNPs." (PMID 23784081, 2013).
glioblastoma (13 papers, 2002 to 2026). The most malignant astrocytic tumor (WHO grade IV). "Our analyses revealed a significant association between the IL-4R gene variant rs1801275 (A/A genotype) and glioblastoma susceptibility." (PMID 41003104, 2025). "However, in our analyses, only the A/A genotype of the IL-4R gene was associated with glioblastoma development." (PMID 41003104, 2025). "Interleukin-4 receptor (IL4R), particularly type-II IL4R, is composed of IL4Rα and IL13Rα1, and it is upregulated in major tumors such as breast, lung, head and neck tumors and glioblastoma compared to their corresponding control tissues." (PMID 37258584, 2023). "Most types of the cancerous cells (lung, colorectal, breast, melanoma, renal cell, ovarian, head/neck cancers, and glioblastoma) express IL4R." (PMID 36009525, 2022). "We have previously shown that a large number (41 of 46 samples) of glioblastoma biopsy samples or primary cell cultures are positive for IL-4Rα and IL-13Rα1 chains as determined by RT–PCR and immunofluorescence analyses." (PMID 11870521, 2002). "Furthermore, there was a positive correlation between the expression of mRNA IL4Rα and IL13Rα1 in glioblastoma multiform." (PMID 33419470, 2021). "For instance IL4R is a biomarker for various aggressive forms of glioblastoma multiforme." (PMID 32181251, 2020). "Two reports, in glioblastoma and lung epithelial cells, showed interactions between the cytoplasmic domains of IL13RA2 and IL4R that interfere with IL4-driven STAT6 signaling." (PMID 40663259, 2025). "Additionally, glioblastoma cells would evade apoptosis in correlation with Il4r expression and enhance growth unlike healthy astroglia." (PMID 32181251, 2020). "The IL-4R/STAT6-dependent pathway induces the downregulation of the miR-17–92 cluster in splenocytes from C57BL/6 mice bearing B16 subcutaneous tumors and in T lymphocytes from glioblastoma multiforme (GBM) patients." (PMID 41582199, 2026).
nasal polyps (13 papers, 2020 to 2026). "Dupilumab, an IL-4Rα antagonist, has shown substantial efficacy in the treatment of chronic rhinosinusitis with nasal polyps (CRSwNP)." (PMID 41281095, 2025). "CM-310 as an IL-4R antagonist showed significant improvements in the nasal polyp score (NPS) and nasal congestion score (NCS) in the phase II study and is currently in a phase III study." (PMID 39600395, 2024). "Dupilumab is a fully human Ig4 monoclonal antibody directed against the interleukin-4 receptor subunit α (IL-4Rα) of IL-4 and IL-13 receptors, blocking the effects of both cytokines, which are involved in T2 inflammation and, therefore, also in Nasal Polyps." (PMID 35743736, 2022). "IL‐13, IL‐4Rα, IL‐13Rα1, and MUC5AC were found to be highly expressed in nasal polyp tissue from patients with eosinophilic chronic rhinosinusitis (ECRS), and IL‐13 expression was positively correlated with MUC5AC expression, indicating that IL‐13 can directly regulate mucin hypersecretion." (PMID 38282195, 2024).
COVID-19 (12 papers, 2020 to 2024). A disease caused by infection with severe acute respiratory syndrome coronavirus 2. "p-STAT6 signaling, the other major mechanism studied in podocytes, was activated downstream of IL-4Rα by COVID-19 cocktails in the ZHX2+/+ podocytes and reduced in ZHX2hypo/hypo cells." (PMID 37040185, 2023). "In addition, Dupilumab, an IL-4Rα inhibitor, was also reported useful for treating COVID-19 patients." (PMID 36992700, 2023). "Therefore, both ZHX- and p-STAT6–mediated mechanisms related to podocyte IL-4Rα are active in COVID-19 models and ZHX mechanisms only in the common cold model." (PMID 37040185, 2023). "ILCp cells from COVID-19 patients showed upregulated expression of IL2RA (adj.p = 0.004), IL4R (adj.p = 2.3e-11) as well as other immune-related genes including TNFRSF25 (adj.p = 4.2e-03) and CCR7 (adj." (PMID 39026668, 2024). "Genes related to T cell responsiveness such as IL21R, IL4R, CXCR4 were also upregulated in COVID-19-infected subjects." (PMID 36881624, 2023). "Clusters containing CD15+ cells were disproportionately enriched in samples from COVID-19 patients, whereas clusters with CD3+, IL4R (CD124) were mostly composed of cells from healthy donors." (PMID 33361110, 2021). "In contrast, the deletion of IL-4Rα expands CD8+ T cells, which may be a reason why IL-4Rα can only play a partial protective role in COVID-19-related cytokine storms." (PMID 38727220, 2024).
nematode infection (11 papers, 2009 to 2023). "Since immunity to the related gastrointestinal nematode parasite N. brasiliensis is also highly dependent on IL-4R/Stat6/IL-13-dependent signaling, we examined whether resistance to nematode infection in the small intestine was affected by Retnla deficiency." (PMID 19381262, 2009). "Together these results demonstrated that high level expression of both Ym1 & RELMα is IL-4Rα-dependent in the context of nematode infection of the lung, extending other studies." (PMID 30500858, 2018). "Although the role of IL-4Rα mediated signaling in initiating and polarizing the development of type 2 immune responses following nematode infections is well established, its requirement in the maintenance of type 2 immune responses is yet to be determined." (PMID 28651009, 2017). "Our studies using administration of recombinant cytokine, a fungal allergen and nematode infection are consistent with these studies and demonstrate that IL‐33‐dependent alternative activation is also reliant on IL‐4Rα in the serous cavities." (PMID 27592711, 2016). "Use of IL-4Rα−/− mice has clearly demonstrated an absolute requirement for IL-4Rα expression in resolving primary nematode infections." (PMID 24204255, 2013). "Additionally, the nematode infection-induced Flt1 mRNA level also showed a partial IL4Rα dependency." (PMID 37215144, 2023). "Interestingly, the production of IL-25 following nematode infection is itself dependent on IL-4Rα, mediated by IL-13 activation of STAT6." (PMID 30238872, 2018). "Data from our laboratory using the filarial L. sigmodontis model suggest that there is a role for IL-4Rα-mediated macrophage activation in the control of this tissue nematode infection but also revealed a key difficulty with the LysMCre mice in the context of IL-4Rα expression." (PMID 25319331, 2014). "Recently, we described that nematode infection induced an IL-4/IL-13-driven intestinal smooth muscle hypercontractility, which was absent in global IL-4Rα−/− mice and reduced in smooth muscle cell-specific IL-4Rα−/− mice." (PMID 23284939, 2012). "However, whether IL-4Rα mediated signaling is required for the maintenance of anti-nematode immunity and the recall of memory responses to secondary nematode infection remains to be determined." (PMID 28651009, 2017). "Particularly, it was still not clear whether IL-4Rα mediated signaling was required for the maintenance of established (already developed) Th2 immune responses and the recall response of memory Th2 immune responses during nematode infections." (PMID 28651009, 2017).
allergic rhinitis (10 papers, 2011 to 2026). Inflammation of the nasal mucous membranes caused by an IgE-mediated response to external allergens. "Allergic rhinitis is associated with IL-4 and IL-13 polymorphism, and dual blockade of IL-4 and IL-13 with dupilumab, an IL-4Rα antibody, is required to inhibit type 2 inflammation such as AR." (PMID 38629073, 2024). "In conclusion, the IL-4Rα-targeting nanobody H5 presents a promising non-invasive treatment strategy for allergic rhinitis." (PMID 39108557, 2024). "All biological functions of IL-4 are mediated by effector IL-4R, including mediating Th1/Th2 imbalance, promoting B cell proliferation and IgE synthesis, which play a crucial role in allergic rhinitis." (PMID 35846137, 2022).
food allergy (10 papers, 2015 to 2025). Gastrointestinal disturbances, skin eruptions, or shock due to allergic reactions to allergens in food. "Still, transplantation of fecal samples from IL-4R mutated mice subjected to food allergy can confer the enhanced Th2 skewing and allergic reactions to wildtype animals suggesting that excessive IL-4R signaling also has a strong impact on the microbiota." (PMID 32922400, 2020). "It is based on a point mutation within the intracellular domain of the IL-4R that has also been found in a subset of patients with food allergy." (PMID 32922400, 2020). "In addition, mice expressing Il-4rαF709 in all cells, a variant of the IL-4 receptor α chain (IL-4Rα) with enhanced IL-4R signaling, have an increased number of intestinal mast cells and show more severe anaphylactic reactions to the food allergy model compared to wild-type mice." (PMID 37296626, 2023). "Genetic susceptibility in Th2 pathway genes (IL4R, IL-4, IL13) dramatically amplified food allergy risk under vitamin D deficiency, with AA/GG/CC genotypes conferring 4- to 26-fold increased susceptibility." (PMID 40927566, 2025). "These interactions demonstrate that genetic susceptibility in Th2 pathway genes (IL4R, IL-4, IL13) dramatically amplifies food allergy risk under vitamin D deficiency, while MS4A2 variants modulate vitamin D’s protective effects." (PMID 40927566, 2025). "The gene–environment interactions we identified reveal a triad of Th2-sensitizing genotypes—IL4R rs1801275 AA, IL-4 rs2243250 CC, and IL13 rs20541 GG—that confer 4- to 26-fold elevated food allergy risk under vitamin D deficiency." (PMID 40927566, 2025). "Omalizumab’s mechanism of IgE blockade differs from that of other biologics under investigation for food allergy, such as dupilumab (an anti-IL-4Rα antibody), which has shown a slower onset of desensitization in Phase 2 trials involving pediatric patients with peanut allergy." (PMID 41208997, 2025). "IL-4R can utilize Janus kinase 1 (JAK1) for signal transduction in food allergies." (PMID 40005151, 2025).